HLA-G (major histocompatibility complex, class I, G)
Diseases named in the same sentence as HLA-G in open-access papers (continued):
Sharing a sentence is not in itself a finding about the gene and the disease.
tumor (continued). "Thus, HLA-G upregulation might represent a mechanism to evade the MHC independent tumor cell killing through NK cells." (PMID 39469714, 2024). "Considering the functional implication of the HLA-G/ILT-2 ligand-receptor axis as an IC in the tumor evolution, we hypothesized that sHLA-G, together with the genetic background of regulatory regions of HLA-G or ILT-2 expression, were relevant for risk assessment of TNBC patients." (PMID 37283737, 2023). "HLA-G-positive cells exhibited a tendency towards widespread metastasis leading to diminished survival rates in xenograft models, demonstrating the role of HLA-G as an immune checkpoint molecule that may influence tumor cell invasion and metastasis." (PMID 38162657, 2023). "In addition, it is possible to speculate that inhibition of HLA-G-positive EV secretion could restore the cytotoxic activities of T cells against tumor cells." (PMID 38162657, 2023). "Consequently, an aberrant HLA-G/sHLA-G expression is considered to allow tumor immune escape." (PMID 37283737, 2023). "However, it should be noted that some tumour-derived EVs also express HLA-G; therefore, HLA-G may be unsuitable as an endogenous placenta biomarker." (PMID 36538060, 2023). "NKG2Anull NK cells exhibit higher cytotoxicity and increased ADCC activity and the potential to kill tumor cells expressing HLA-E or HLA-G; however, the proliferative capacity of NKG2Anull NK cells may be poor in HLA-Enull tumor tissues because of strong inhibitory signals." (PMID 37144558, 2023). "Therefore, we considered that combining the PD‐L1 targeting strategy with HLA‐G Nb‐CAR might represent an ideal approach to mitigating the possibility of immune escape in tumor cells." (PMID 37078788, 2023). "The identification of human leukocyte antigen-G (HLA-G) as a key factor in this process suggests that targeted therapies aimed at disrupting the sEV-mediated delivery of HLA-G may hold promise for enhancing the effectiveness of anti-tumor immune responses in the context of RCC." (PMID 37469514, 2023). "According to the fact that HLA-G is a normal immune signal that can block the immune response, many recent studies have consistently claimed that HLA-G could be a new immune checkpoint molecule in tumours." (PMID 35924232, 2022). "Given the correlation between IDO and HLA-G in different human tumors, anti-HLA-G antibodies may be used in combination with these inhibitors, such as Indoximod and Epacadosat, to further increase their effect on the rescue of anti-tumor immune response." (PMID 35328349, 2022). "This is supported by the finding that the high levels of HLA-G observed in the tumor microenvironment, induced by the differentiation of cancer cell lines, may increase the expression of PD-1 on T lymphocytes, which may be, in turn, suppressed by cancer cells expressing high levels of PD-L1." (PMID 35328349, 2022). "Also, during this phase, epigenetic mechanisms lead to a process of histone hypomethylation and acetylation that favors the expression of HLA-G, which competes with the antigenic presentation by classical histocompatibility molecules, promoting a process of tumor tolerance." (PMID 35154112, 2022). "HLA-G is an immune checkpoint molecule with immunosuppressive and anti-inflammatory activities, and its expression and level of its soluble form (sHLA-G) may play an important role in tumor prognosis." (PMID 35626255, 2022). "Thus, the expression of HLA-G varies depending on the location within the tumour." (PMID 35027037, 2022). "So far, dociparstat showed limited efficacy as monotherapy, but we may speculate that its combined administration with different anti-TIM-3 antibodies, already approved for clinical purposes, plus anti-HLA-G antibodies may result in increased anti-tumor efficacy." (PMID 35328349, 2022). "Tumor cells may use HLA-G, ligand for ILIRB1 to inhibit NK cells." (PMID 35652109, 2022).
tumor (continued). "The vast majority of HLA-G detection studies use immunohistochemistry as the main method, but each laboratory uses different antibodies and variable experimental conditions (incubation times, antibody concentration, etc), even when analyzing the same type of tumor." (PMID 35154112, 2022). "In addition, HLA-G has been detected in extracellular vesicles (EV) in the supernatant of tumor cells including melanoma cells and might play a role in cancer immune escape by inhibiting immune cells in the TME even at distal sites." (PMID 35185904, 2022). "Furthermore, the HLA-G-driven up-regulation of PD-1 on T lymphocytes may render them anergic in the presence of tumor cells expressing PD-L1/L2." (PMID 35328349, 2022). "Therefore, we critically assessed whether the use of certain HLA-G quantification methods and the percentage of HLA-G-positive tumours might have had an influence on the eventual clinical outcome of CRC patients." (PMID 34361031, 2021). "This may partly explain variability in range of percentage reported HLA-G-positive tumour samples." (PMID 34361031, 2021). "Furthermore, we also demonstrated a reasonable strategy for upregulating cell surface expression of HLA-G on tumor cells via pretreatment with low-dose chemotherapeutic agents; this pretreatment maximizes the antitumor efficacy of the CAR-NK cells both in vitro and in vivo." (PMID 34663641, 2021). "However, HLA-G may be induced in numerous malignant tumors, such as glioblastoma and melanoma tumors, contributing to tumor immune escape." (PMID 34884849, 2021). "In addition, increased presentation of HLA-G on tumor cells results in the failure of NK cell-based immunotherapy, 26 which may explain why Dox-treated HLA-G knockdown MDA-MB-231 cells were more sensitive to mock control NK-induced cytotoxic killing." (PMID 34663641, 2021). "Opposed to already existing HLA-G-related reviews, both statistically significant as well as non-significant analyses concerning the association between tumour HLA-G expression and clinical patient outcome were included to obtain the most complete picture on this association as possible." (PMID 34361031, 2021). "Therefore, it has been proposed that the HLA-G blockade could be beneficial in any neoplasia that expresses HLA-G as an evasion mechanism of immune surveillance." (PMID 34773056, 2021). "Consequently, it remains elusive whether HLA-G expression by carcinomas functions as an immune checkpoint molecule affecting a tumour-immune response." (PMID 34361031, 2021). "However, after stratification of the patient group for loss of HLA-class I expression, HLA-G expression was significantly associated with shorter RFP compared to patients without HLA-G-expressing tumour cells." (PMID 34361031, 2021). "Furthermore, previous studies show that HLA-G expression can be induced in different tumor cell lines and mesenchymal stem cells by treatment with the demethylating agent 5-aza-2′-deoxycytidine (5-aza-dC) indicating that HLA-G expression is regulated partly by methylation-mediated repression." (PMID 32560316, 2020). "Furthermore, we have shown here that HLA-G and PD-L1 increase during mitosis; these findings suggest that Ki-67 may also be used as a marker of immune resistance in tumor nodules." (PMID 32961872, 2020). "While these two higher molecular weight proteins have been previously been detected in human tumor exudates and identified as “HLA-G-like” molecules using a number of HLA-G antibodies for verification, we wish to ascertain this fact and thus performed knockdown with siRNA specific for HLA-G." (PMID 32708387, 2020). "Therefore, the roles of HLA-G in pregnancy may provide clues for further understanding of tumor immunology." (PMID 33193435, 2020).
tumor (continued). "However, mRNA expression is not directly correlated or associated with HLA-G protein expression, limiting the estimation of HLA-G actual expression in tumor tissue, particularly concerning the presence and percentage of the non-canonical isoforms, for which the antibodies are scarce or inexistent." (PMID 32922387, 2020). "In malignancies, aberrant HLA-G expression was preferentially detected in tumor tissues but was rarely detected in normal or adjacent non-tumorous tissues, which indicates that HLA-G might play a key role in tumor development." (PMID 32670296, 2020). "HLA-G tumor expression could function as targeting molecule for such antibodies." (PMID 33213057, 2020). "Different responses to checkpoint inhibitor therapy could be a consequence of heterogeneous intra- and inter-tumor expression of different types of checkpoint molecules, although data on the expression status of HLA-G, CTLA-4 and PD-L1 in cancers are rather limited." (PMID 32670296, 2020). "By the process of trogocytosis, on the one hand, very few HLA‐G‐positive tumor cells may rapidly generate a large number of HLA‐G‐positive cells, which can directly inhibit antitumor immune responses through the interaction with the immune inhibitory receptor ILTs." (PMID 31489189, 2019). "Fortunately, HLA-G down-regulation with RNA interference or antibody blockade can recover the functions of immune effectors and prevent tumor reoccurrence, raising the possibility that HLA-G/ILTs interaction blockade could be a potential immuno-therapeutic strategy for cancer treatment." (PMID 30319626, 2018). "However, because ILT2 is normally only expressed by a minority of CD4+ T cells (0–4%) and CD8+ T cells (5–20%), variations in its expression might impact HLA-G capability to inhibit anti-tumor effectors." (PMID 30237859, 2018). "Consequently, tumor cells that fail to present surface neoantigens due to an altered classical HLA class I complex can avoid killing by T cells, and aberrant induction of HLA-G expression can suppress the functions of various immune cells for immune escape." (PMID 30319626, 2018). "In this in-depth study, expression levels of HLA-G isoforms such as HLA-G1, -G5, and -G6 were highly variable among tumors from different patients (intertumor heterogeneity) and among distinct areas or subcellular locations in the same tumor (intratumor heterogeneity)." (PMID 30319626, 2018). "Thus, in this study, we investigated whether HLA-G expression by the tumor and/or in plasma, and ILT2 expression by the peripheral T cells, taken independently or together, was of interest for the prognosis prediction of NMIBC." (PMID 30237859, 2018). "The results showed that mAbHLA−G/MTX/PLGA NBs could specifically transport to the HLA-G positive tumor cells in vitro or tumor tissues in vivo in a murine model, and the released MTX from the NBs could kill the residual tumor cells and inhibit the reoccurrence of tumors." (PMID 30319626, 2018). "Moreover, it has also been reported that HLA-G can up-regulate tumor-promoting agents such as MMPs." (PMID 30319626, 2018). "Even though we used large tumor biopsies obtained by open surgery, HLA-Gpos areas in individual tumors may have been overlooked, resulting in an underestimation of the true proportion of HLA-G-expressing EwS." (PMID 29464090, 2018). "Thus, soluble factors released by CAR T cells can mediate HLA-G upregulation by the tumor cells." (PMID 29464090, 2018). "This knowledge could assist us to induce HLA-G when immune suppression is needed (e.g., pregnancy, organ transplant, and autoimmunity) or to inhibit its expression when can be potentially harmful (e.g., tumor or chronic viral infections)." (PMID 28769934, 2017). "Moreover, different proportion of lesion HLA-G expression has been found between different cancer types, between tumors from individuals with the same type of cancer, and even between the different intra-tumor areas within a single sample." (PMID 29296176, 2017).
tumor (continued). "Thus, it's reasonable to speculate that the different proportion of HLA-G expression in tumor lesions could influence disease progression and clinical outcome." (PMID 29296176, 2017). "Furthermore, the reported HLA-G regulatory miRs exert tumor suppressive activity." (PMID 27057628, 2016). "Therefore, hypoxia environment combined with anticancer therapy might favor HLA-G expression and consequently tumor progression." (PMID 27577073, 2016). "However, the increased tumor burden might be correlated to a higher release of tumor-derived factor(s) that, in turn, can upregulate HLA-G and HLA-E production by BM stromal cells." (PMID 27610393, 2016). "Therefore, by transferring HLA-G and possibly other immune-inhibitory molecules, tumor cells may share some of their immune escape strategies, as our in vitro model showed here." (PMID 25887663, 2015). "Thus, HLA-G expression by malignant cells may prevent tumor immune eradication by inhibiting the activity of tumor infiltrating NK, cytotoxic T lymphocytes (CTL), and APCs." (PMID 25887663, 2015). "As a result, HLA-G detected with mAb 4H84 and HGY could only present the combination of certain types of HLA-G isoform (total HLA-G) expression; however, leaves the type of isoform expression in tumour lesions undistinguished, such as the status of lesion sHLA-G isoform expression." (PMID 25689063, 2015). "Among key regulatory processes involved in HLA-G expression, DNA methylation (CpG) and hypoacetylation of H3 and H4 histones at the HLA-G locus have been associated with the absence of HLA-G expression commonly observed in cultured tumor cells expressing or not classical HLA molecules." (PMID 24800261, 2014). "Both IL-10 and HLA-G may be produced by tumor cells but also by tumor-infiltrating leucocytes." (PMID 24800261, 2014). "Notably, patients with tumors co-expressing HLA-G and -E display the worst clinical outcome, thus suggesting that the two molecules may co-operate shutting down NK cell-mediated anti-tumor immune response." (PMID 25202308, 2014). "Of note, discrepancy between solid and liquid tumors may be due to the nature of malignant cells: in hematological malignancies, tumor cells are immune cells able to express HLA-G receptors and HLA-G may have an unexpected role through inhibition of neoplastic cell proliferation." (PMID 24800261, 2014). "Strategies aimed at blocking HLA-G expression by using RNA interference or HLA-G function by using specific antibodies may enhance the immune clearance of HLA-G+ tumor cells since all cell subsets involved in tumor rejection can express at least one receptor for HLA-G." (PMID 24800261, 2014). "Furthermore, tumor-expressed HLA-G induced suppressive MDSC and tumor growth in vivo." (PMID 24348482, 2013). "This study did not support the hypothesis that spontaneous de-methylation events in the HLA-G promoter play a primary role in the development of precancerous cervical lesions through HLA-G re-expression and consequential promotion of viral and tumor escape from immunosurveillance." (PMID 23265140, 2012). "HLA-G is well known for its immuno-tolerogenic properties utilized by neoplastic cells in many malignancies where its expression may represent one of the various mechanisms used by tumor cells to thwart the immune response." (PMID 22640987, 2012). "The tumor-infiltrating T-cells, as well as CAR gene-modified effectors, also play an important role in providing response to EwS cells, which upregulates HLA-G expression, suggesting the higher efficacy of cellular immunotherapies in EwS." (PMID 40242222, 2025). "The interaction between HLA-G and KIR likely plays a critical role in inhibiting NK cell activity, allowing tumor cells to evade destruction." (PMID 41234446, 2025). "JNJ-78306358 is a first-in-class HLA-G x CD3 BiTE that binds with weaker affinity to CD3 expressed on T cells and higher affinity to HLA-G-expressing tumor cells." (PMID 40565299, 2025).
tumor (continued). "In tumors, top DEGs included HLA-G (FC = 18.13; FDR = 1.72 × 10−2), which is known to promote tumor immune evasion, and complement receptor CR2 (FC = 16.45; FDR = 4.15 × 10−2)." (PMID 39951265, 2025). "The findings of this study indicate that HLA-G levels are markedly increased in CRC patients, indicating its critical role in helping tumor cells evade immune detection." (PMID 41234446, 2025). "HLA-G-based therapies, such as CAR-NK cells targeting HLA-G, show promise in overcoming tumour immune evasion." (PMID 40155873, 2025). "Certain oncogenic lncRNAs modulate tumor immunogenicity within tumor cells by either suppressing tumor antigen production directly or enhancing the expression of immune checkpoints (e.g., PD-L1, IDO) and HLA-G indirectly." (PMID 41584608, 2025). "More recently, trispecific engagers incorporating PD-L1, HLA-G, and CD3 have been developed to overcome tumor heterogeneity, particularly in lung cancer." (PMID 41445738, 2025). "In most cases, the HLA-G/ILT interaction can promote cancer cells to evade immune surveillance and anti-tumor immunity." (PMID 38542078, 2024). "The expression of HLA-G has been demonstrated to be enhanced through HIF-1 under hypoxia and hypoxia-simulating conditions in the tumor microenvironment." (PMID 38877399, 2024). "The relationship between CD147 and HLA-G is seen in cancer cells where CD147 is emerging as a protein capable of regulating cancer hallmarks, such as tumor angiogenesis, a process in which CD147 acts through the regulation of VEGF/VEGFR and ADAM-12." (PMID 39358558, 2024). "It was demonstrated that the anti-HLA-G constructs convert inhibitory signals into activating signals, initiating robust cytotoxicity of engineered CAR-NK cells upon contact with tumor cells." (PMID 38310272, 2024). "Then, we established a xenograft tumor model using control and IDO-1 knockdown MDA-MB-231 cells, followed by treatment via adoptive transfer of NK cells and/or injection with the HLA-G antibody." (PMID 37981615, 2024). "In this study, we found that IDO-1, upon induction by tumor environmental cytokines like IFN-γ, can suppress the tumoricidal capacity of NK cells by up-regulating HLA-G." (PMID 37981615, 2024). "Many are designed to bring immune cells in proximity with tumor cells by targeting both immune markers (CD137/4-1BB, CD27, PD-1, OX-40) and tumor markers (B7-H3, CD47, PD-L1, 5T4, ROR1, claudin, GPC3, HLA-G, PSCA)." (PMID 38254823, 2024). "HLA-G is highly expressed in many solid tumor cells and is positively correlated with infiltrating immune cells in the tumor microenvironment, which may be a means for tumor cells to avoid immune system regulation by inhibiting natural killer and T cell-mediated lysis." (PMID 38427106, 2024). "Since PD1/PDL1 and HLA-G/ILT2 appear to function as independent mechanisms, the combination of both therapies has been shown to restore antitumor activity in a variety of tumor cells." (PMID 38391781, 2024). "The relationship between high expression levels of sHLA-G and the decrease in OS and DFS observed in our results can be explained by the immune suppression induced by the interaction between tumor HLA-G and ILT-2/-4 expressed on the immune cells surface." (PMID 37573450, 2023). "As an inhibitor of B-cell growth, HLA-G probably exerts an inhibitory effect on tumor growth by interacting with LILRB1, suggesting that HLA-G-LILRB1 axis can be applied to the treatment of B-cell malignancies." (PMID 36882399, 2023). "Considering the HLA-G 5′URR, the G0104a haplotype was underrepresented among patients presenting tumor multicentricity (OR = 0.3360, 95% CI = 0.1446–0.7810, p = 0.0089) compared to patients without this manifestation." (PMID 37629044, 2023). "Meanwhile, HLA‐G, a member of the MHC class I, is a well‐established immune checkpoint that plays an important regulatory role in tumour immune response." (PMID 36408734, 2023).